BAK1 (BCL2 antagonist/killer 1)
Diseases named in the same sentence as BAK1 in open-access papers (continued):
Sharing a sentence is not in itself a finding about the gene and the disease.
infection (56 papers, 2007 to 2025). The state of being infected such as from the introduction of a foreign agent such as serum, vaccine, antigenic substance or organism. "Only the ALD1 mutation adversely affected the level of BAK1 protein during PsmES4326/AvrRpt2 infection." (PMID 36523630, 2022). "The MTI coreceptor double mutant, bak1‐5/bkk1‐1, exhibits a remarkable decrease in Fv/Fm compared to control plants during infection, underlining the importance of MTI‐mediated signalling in chloroplast immunity." (PMID 35892221, 2022). "Nicotiana benthamiana plants with mutated or silenced coreceptors of pattern recognition receptors, SOBIR1 and BAK1, showed similar susceptibility as control plants to infection by B. cinerea wild type and a 12x deletion mutant." (PMID 35239739, 2022). "Even, BAK1 influences pathogen-induced plant cell death and accordingly some bak1-deletion alleles (e.g., bak1-3 and bak1-4) show enhanced cell death upon infection." (PMID 27446127, 2016). "Four genes encoding BAK1 RLKs were differentially expressed in both or one of the cultivars in response to Pcb1692 infection." (PMID 28066465, 2016). "BAK1/SERK3 is also implicated in cell-death control, and bak1 knock-out mutants have a spreading lesion phenotype upon pathogen infection and premature senescence." (PMID 23615468, 2013). "It is believed that such an enhanced PCD phenotype in bak1 mutant upon pathogen infection is caused by the subsequent dysfunction of BAK1/BON1 suppressed cell death, which in turn activates the PEPR signaling pathway to reversely trigger cell death and to retain immunity to biotrophic pathogens." (PMID 30671069, 2018). "Studies have shown that BAK1-deficient mutants display enhanced susceptibility to infection by necrotrophic fungal pathogens, but increased resistance to biotrophic pathogens, suggesting opposing roles of BAK1 in resistance to necrotrophic and biotrophic pathogens." (PMID 30563020, 2018). "Moreover, tomato plants silenced in BAK1, showed higher susceptibility to infection with Verticillium indicating that BAK1 is involved in Ve1-induced defense responses in tomato." (PMID 23720666, 2013). "In our results, for the transgenic plants, FLS2 and BAK1, which are sensitive to pathogen infection, were activated, and the genes were up- and down-regulated, respectively." (PMID 36982808, 2023). "By using plants mutated or silenced in two well-characterized PTI coreceptors, SOBIR1 and BAK1, for infection by B. cinerea, we evaluated the possible role of PTI for CDIP-mediated necrosis induction." (PMID 35239739, 2022). "Downstream signal transduction of pathogen infection requires BAK1, a central regulator of plant immunity which was found to be highly up-regulated in Tetep." (PMID 33672641, 2021). "Pathogen infection and the FLS2-mediated ligand binding leads to the FLS2-BAK1 association, followed by BAK1-mediated phosphorylation and activation of BIK1, which dissociates from the complex." (PMID 30205610, 2018). "bak1 single mutants developed a type of uncontained PCDs upon infection with virulent necrotrophic pathogens, which differs from both necrotizing elicitor- and SA-inducible PCD." (PMID 30671069, 2018). "Multiple signaling components distinct from the BRI1 pathway are also engaged by BAK1 to trigger PCD upon pathogen infection." (PMID 30671069, 2018). "Research has shown that BAK1 functions in pathways involved in plant resistance to pathogen infection." (PMID 29284401, 2017). "Bak1 mutants develop spreading necrosis after the triggering of apoptosis by infection with B. cinerea." (PMID 24387266, 2014). "BAK1 is also involved in cell death control as bak1 knock-outmutants have a spreading lesion phenotype upon pathogen infection and prematuresenescence." (PMID 21593986, 2011). "We found that DCs lacking Bak1/Bax or Casp3/7 showed increased viability upon infection compared to the WT control, although infection still caused a decrease in viability compared to uninfected samples." (PMID 39772728, 2025).
infection (continued). "The IDA-HAE/HSL/BAK1/SERKs-mediated immune signaling may protect against pathogen infection during cell separation." (PMID 38416059, 2024). "BAK1 showed significantly upregulated expression after infection." (PMID 39574453, 2024). "At primary infection sites, PTI, DTI, and ETI responses cause production of mobile signals including eNAD(P) and NHP22,51,52, which are subsequently transported to systemic tissues where eNAD(P) binds to and activates its receptor complex LecRK-VI.2/BAK1." (PMID 37891163, 2023). "Sorting out primary and secondary effects in natural infections and specificities for PRRs and phytocytokines receptors might solve the jigsaw of BAK1/SERK-related receptor complexes in plant immunity." (PMID 37747566, 2023). "However, overexpression of HopB1 leads to autoimmune cell death, indicating that perturbation of BAK1 during infection can induce ETI-like autoimmune cell death." (PMID 37747566, 2023). "During infection, HopB1 cleaves activated BAK1, resulting in reduced PTI-type defense responses." (PMID 37747566, 2023). "After infection, however, BAK1 proteins accumulated to the WT level in npr1 and sid2 mutants, and BAK1 levels in the double mutants could not be distinguished from npr1 and sid2 mutants." (PMID 36523630, 2022). "Interestingly, Fv/Fm dynamics in DC3000hrpA challenged bak1‐5 leaves pretreated with flg22 or elf18 before infection were wild type in response, whereas chitin pretreatment only partially protected against Fv/Fm suppression in the bak1‐5 background." (PMID 35892221, 2022). "The accumulation level of ICAs was even higher in pen2 bak1–5 than pen2 at 48 hpi, which might be due to enhanced infection in pen2 bak1–5." (PMID 33452278, 2021). "Similarly, silencing BAK1 in N. benthamiana also leads to enhanced PCD upon infection with Hyaloperonospora parasitica." (PMID 30671069, 2018). "Provided the diverse roles of BAK1 in distinctive signaling pathways, whether these BAK1-targeting effectors benefit infection through a potential disruption of BR signaling, as well as other pathways such as the DAMP signaling, requires careful investigation." (PMID 26879412, 2016). "Notably, these phytocytokine precursor-encoding genes often possess unique tissue expression patterns related to specific stages of plant growth and development or upon infection, while BAK1/SERKs are abundantly expressed in various tissues across different developmental stages." (PMID 38416059, 2024). "Therefore, BAK1 is involved in primary and secondary events under natural infection conditions." (PMID 37747566, 2023). "Defense genes associated with CEBiP, BAK1, NB-LRR proteins, PR proteins, transcription factor and cell wall lignification were expressed stronger in ‘Yueyoukang 1’ than ‘Brazilian’, indicating that these genes play important roles in banana against Foc4 infection." (PMID 24086302, 2013). "During the late phase of infection, there was a rebound in VDAC expression, induction of BAK1 (+1.16 at 48 h), and a significant reduction in PPARGC1A at 72 h (−1.63), which reduced mitochondrial resiliency." (PMID 41568347, 2025). "To minimize PTI-induced FLS2 accumulation during infection, we used bak1-5 bkk1 double mutants for the infection assay, as flg22-, elf18-, and pep1-mediated PTI responses are dramatically reduced in bak1-5 bkk1 mutant." (PMID 39431742, 2024). "The increased expression of BAK1, MKK1/2, MKS1, MPK, MPK3/6, ACS6, WRKY TF, PR1, and FRK1 in NOWP and/or NOWS proposes that N. indicum responds to witches’ broom infection by both the early and late defense responses." (PMID 35701735, 2022). "For example, BAK1 is a general co‐receptor for multiple LRR‐type receptors that have various functions, whereas the bak1 mutant only develops necrosis upon pathogen infection and the bak1 bkk1 double mutant exhibits uncontrolled cell death." (PMID 32924279, 2020).
infection (continued). "Moreover, upon infection with a necrotrophic pathogen, Alternaria brassicicola, bir2 mutants had enhanced cell death and susceptibility to this pathogen, whereas BIR2 interacts with BAK1 and suppresses the autoimmune cell death response in the absence of PAMPs." (PMID 30671069, 2018). "On the other hand, upon pathogen infection, bak1bir3 showed increased pathogen-inducible PCD; upon ligand perception, overexpression of BIR2 suppressed the BAK1/FLS2 (PRR) complex formation." (PMID 30671069, 2018). "Consistent with the role played by BAK1, we identified a leucine-rich repeat receptor-like kinase, termed NILR1 that is specifically regulated upon infection by nematodes." (PMID 28406987, 2017). "Here, we investigated the potential roles of receptors FLS2, BAK1, and BIK1 in the infection of P. brassicae cruciferous plants." (PMID 27679580, 2016). "Therefore, the final balance of the crosstalk between BAK1 and SYMRK would be that BAK1, a negative regulator of rhizobial infection, is inhibited by SYMRK, allowing the infection and nodulation to take place." (PMID 36928335, 2023). "In addition, the FLS2, BAK1, BRI1, and MYB61 genes were significantly up-regulated across all infection stages in our results." (PMID 34630478, 2021). "Additionally, Systemin treated plants display enhanced BAK1 and BIK1 gene expression following infection as well as increased production of ROS after PAMP treatment suggesting that Systemin sensitizes Arabidopsis perception to pathogens and PAMPs." (PMID 32536929, 2020). "Defense responses are not constitutively activated in the bak1 and bkk1 single mutants, but uncontrolled spreading of necrosis occurs in bak1 knockout mutant plants upon infection by necrotrophic pathogens." (PMID 27909443, 2016). "Specifically, eleven BAK1 genes, two BRI1 genes, three EFR genes and seven FLS2 genes were significantly up-regulated in the ‘Zifengyu’ cultivar during the early stages of infection, but they were gradually up-regulated in the ‘Dafugui’ cultivar during the same stage." (PMID 26208357, 2015). "Up-regulation of apoptotic genes like BAX, BAK1 in H5N1 (WB-NIV2664) but not in IBCDC-RG7 infection could be a part of cytokine mediated response." (PMID 20828378, 2010). "Castanea sativa had no BAK1 ortholog detected in the transcriptome and few putative PRR genes DE during infection." (PMID 39188543, 2024). "In Arabidopsis, loss function of BIR1 leads to constitutive activation of cell death, enhanced accumulation of SA and H2O2, and induction of PR genes dependent on BAK1, EDS1, PAD4, and SOBIR1 in the absence of pathogen infection." (PMID 37047410, 2023).
bacterial infection (2 papers, 2015 to 2019). "Upon bacterial infection, flg22 is sensed by the FLS2 extracellular domain, which in turn recruits BAK1 into an active immune complex that phosphorylates NIK1 on its crucial Thr474 residue." (PMID 31676803, 2019).
neurological diseases (1 paper, 2020). "Bcl2 family-related proteins [Bcl2, Bcl-xL (also known as Bcl2l1), Bax and Bak1] play an essential role in the neuronal apoptotic pathway in various neurological diseases." (PMID 32540990, 2020).
BAK1 also shares sentences with these, for which no sentence is quoted: glioma (4 papers); colorectal cancer (3); liver cancer (3); adenocarcinoma (2); cardiac hypertrophy (2); colitis (2); Ewing sarcoma (2); idiopathic pulmonary fibrosis (2); polycystic ovary syndrome (2); acute lymphoblastic leukemia (1); acute promyelocytic leukemia (1); bacterial sepsis (1); bladder cancer (1); bladder tumors (1); blood cancer (1); breast tumors (1); chronic myeloid leukaemia (1); colorectal tumors (1); COVID-19 (1); cutaneous squamous cell carcinoma (1); cutaneous T-cell lymphoma (1); Dengue hemorrhagic fever (1); diffuse large B-cell lymphoma (1); dysplasia (1); esophageal squamous cell carcinoma (1); gonococcal infection (1); heart failure (1); hematologic cancer (1); HIV-1 infection (1); Hodgkins lymphoma (1).
A further 26 diseases each share a sentence with BAK1 in 1 paper.